NDUFB9 (NADH:ubiquinone oxidoreductase subunit B9)
Description:
Accessory subunit of the mitochondrial membrane respiratory chain NADH dehydrogenase (Complex I), that is believed to be not involved in catalysis. Complex I functions in the transfer of electrons from NADH to the respiratory chain. The immediate electron acceptor for the enzyme is believed to be ubiquinone.
Synonyms: CI-B22; LYRM3; UQOR22; B22; MC1DN24
Tractability: Small molecule: an approved drug acts on it; a structure with a bound ligand is known. Antibody: UniProt places it where antibodies can reach, with high confidence. PROTAC: ubiquitination databases record sites on it; its protein half-life has been measured.
Target class: Enzyme; Oxidoreductase
Gene: Protein-coding gene on chromosome 8 (124,539,101 to 124,580,648, forward strand). Ensembl gene ENSG00000147684.
Subcellular location: Mitochondrion inner membrane
Subcellular location (Human Protein Atlas): Mitochondria
Pathways (Reactome):
Metabolism: Complex I biogenesis; Respiratory electron transport
Gene Ontology:
Molecular function: protein binding; NADH dehydrogenase (ubiquinone) activity
Biological process: aerobic respiration; mitochondrial electron transport, NADH to ubiquinone; proton motive force-driven mitochondrial ATP synthesis; sensory perception of sound; proton transmembrane transport
Cellular component: mitochondrial inner membrane; mitochondrion; respiratory chain complex I
Genetic constraint (gnomAD): Loss-of-function variants: 22 observed, 27.02 expected, observed/expected ratio (o/e) 0.81, 90% interval 0.58 to 1.16. The upper end of that interval is the gene's LOEUF score, 1.16, which puts it in group 5 of 6, group 1 being the genes least tolerant of losing a copy. Missense variants: 200 observed, 231.33 expected, observed/expected ratio (o/e) 0.86, 90% interval 0.77 to 0.97. Synonymous variants: 80 observed, 89.18 expected, observed/expected ratio (o/e) 0.9, 90% interval 0.75 to 1.08.
Gene-disease validity (ClinGen):
ClinGen rates the evidence that NDUFB9 causes each of these diseases.
mitochondrial disease (autosomal recessive): Limited.
Homologues: Orthologues: chimpanzee NDUFB9 (99% identical), macaque NDUFB9 (94% identical), pig NDUFB9 (92% identical), dog NDUFB9 (91% identical), rabbit NDUFB9 (89% identical), guinea pig NDUFB9 (85% identical), mouse Ndufb9 (85% identical), rat Ndufb9 (85% identical), tropical clawed frog ndufb9 (77% identical), zebrafish ndufb9 (75% identical), Drosophila melanogaster ND-B22 (34% identical), Caenorhabditis elegans C16A3.5 (30% identical).
Diseases named in the same sentence as NDUFB9 in open-access papers:
NDUFB9 is named in the same sentence as 32 diseases in open-access papers, as found by Europe PMC text mining. Sharing a sentence is not in itself a finding about the gene and the disease. The quoted sentences say what the papers report.
breast carcinoma (8 papers, 2015 to 2024). "Inactivation of tumor suppressor genes such as RPS7, MRPL39, MRPS23, ME2, and NDUFB9 were diagnosed with the development of many cancer types such as colorectal cancer, gastric cancer, breast cancer, and pancreatic cancer, but loss of these genes may be responsible for the development of GBM." (PMID 31137733, 2019). "NDUFB9 is a component of NADH dehydrogenase in the respiratory chain complex I. NDUFB9 was downregulated in highly metastatic breast cancer and silencing its expression in MDA-MB-231 cells promotes proliferation, migration, and invasion." (PMID 38283944, 2023). "Down-regulation of NDUFB9 was demonstrated to promote breast cancer cell proliferation and metastasis." (PMID 37405988, 2023). "In the present study, we showed, for the first time, that NDUFB9 was a suppressor of MDA-MB-231 breast cancer cell proliferation, migration and invasion." (PMID 26641458, 2015). "However, in breast cancer, NDUFB9 serves as a prognostic protective gene, exhibiting inconsistency with the outcomes of the current investigation." (PMID 38506898, 2024). "Moreover, NDUFB9 was down-regulated in highly metastatic breast cancer cells compared with parental breast cancer cell line which indicating that NDUFB9 promoted breast cancer cells proliferation, migration and invasion." (PMID 27768723, 2016).
Alzheimer disease (3 papers, 2019 to 2023). A progressive, neurodegenerative disease characterized by loss of function and death of nerve cells in several areas of the brain leading to loss of cognitive function such as memory and language. "Notably, we identified that CO therapy decreased the expression of genes encoding ETC complex I genes: NDUFB4, NDUFS2, NDUFAB1, NDUFA6, NDUFB9, also enriched in Parkinson’s, Huntington’s and Alzheimer disease pathways." (PMID 31615996, 2019).
osteosarcoma (3 papers, 2023 to 2024). A usually aggressive malignant bone-forming mesenchymal neoplasm, predominantly affecting adolescents and young adults. "Among them, COX6A2, MTHFD2, and NDUFB9 were positively correlated with risk scores, suggesting that they were risk genes for unfavorable prognosis among individuals with osteosarcoma." (PMID 38506898, 2024). "Among them, FDX1, TOMM20 and NDUFB9 were associated with poor survival of osteosarcoma while COX11, MFN2 and ATP6V1E1 predicted good." (PMID 37405988, 2023). "Furthermore, the current study also highlighted the function of NDUFB9 as a prognostic risk gene for osteosarcoma." (PMID 38506898, 2024). "In the osteosarcoma tissue, FDX1, TOMM20, and NDUFB9 are all overexpress to promote the development of osteosarcoma." (PMID 38800967, 2024). "In this research, five oxidative phosphorylation genes linked to the prognosis of individuals with osteosarcoma were screened out, including ATP6V0D1, LHPP, COX6A2, MTHFD2, and NDUFB9." (PMID 38506898, 2024). "The expression of FDX1, COX11, MFN2, TOMM20 and NDUFB9 at mRNA level was elevated in osteosarcoma cells compared with normal osteoblast hFOB1.19." (PMID 37405988, 2023). "In this study, a total of six key cuproptosis-mitochondrion genes (FDX1, TOMM20, NDUFB9, COX11, MFN2 and ATP6V1E1) associated with prognosis of osteosarcoma were finally identified." (PMID 37405988, 2023). "A total of six cuproptosis-mitochondrion genes (FDX1, COX11, MFN2, TOMM20, NDUFB9 and ATP6V1E1) were identified to be associated with the prognosis of osteosarcoma." (PMID 37405988, 2023). "Finally, it was experimentally verified that the expression of FDX1, COX11, MFN2, TOMM20 and NDUFB9 at mRNA levels was elevated in osteosarcoma." (PMID 37405988, 2023). "However, we are not aware of any study on the immunological aspects of FDX1, TOMM20, NDUFB9, COX11, MFN2 and ATP6V1E1 in osteosarcoma for the time being, which is a direction we need to study subsequently." (PMID 37405988, 2023).
gastric cancer (2 papers, 2019 to 2022). A primary or metastatic malignant neoplasm involving the stomach. "These potentially new gastric cancer driver genes, as well as genes with high nonclonal mutation frequency, such as STK11, GPS2, NDUFB9, and AXIN2, represent good candidates for inclusion in future studies of gastric tumorigenesis." (PMID 36970058, 2022).
melanoma (2 papers, 2018 to 2024). A malignant, usually aggressive tumor composed of atypical, neoplastic melanocytes. "The occurrence of this mutation reduced transcriptional activity, suggesting it may lead to decreased NDUFB9 levels in melanomas." (PMID 29735924, 2018).
ovarian carcinoma (2 papers, 2025). A malignant neoplasm originating from the surface ovarian epithelium. "Copy number alterations in genes such as PDCD10 and NDUFB9 (amplifications) and NDUFS7 and ZBTB7A (deletions) were also identified, particularly in ovarian cancer, suggesting their contributions to genomic instability." (PMID 40396172, 2025).
prostate carcinoma (2 papers, 2015 to 2023). A carcinoma that arises from epithelial cells of the prostate gland. "More importantly, both H3K27ac and RNA-seq data showed a much higher signal in the cancer cell line compared to the healthy cell line, indicating a possible effect of this PC-associated duplicated CNVR in enhancing the expression of NDUFB9 and MTSS1 genes in prostate cancer." (PMID 36768794, 2023).
cutaneous melanoma (1 paper, 2022). A primary melanoma arising from atypical melanocytes in the skin. "NDUFB9 modulates mitochondrial function to affect the prognosis of cutaneous melanoma and uveal melanoma." (PMID 35887658, 2022).
endometrial cancer (1 paper, 2022). Primary or metastatic malignant neoplasm involving the endometrium (mucous membrane that lines the endometrial cavity). "EIF2S2, SNRPC, PRELID1, and NDUFB9 were all up-regulated in endometrial cancer tissues, according to PCR results." (PMID 36185238, 2022). "SNRPC, PRELID1, EIF2S2, and NDUFB9, four of the model’s genes, were discovered to have higher levels of expression in endometrial cancer than in nearby tissues (*P<0.05, **P<0.01, ***P<0.001)." (PMID 36185238, 2022). "We created an LLPS-related predictive model for endometrial cancer by extensive study, and it consists of four genes: EIF2S2, SNRPC, PRELID1, and NDUFB9." (PMID 36185238, 2022).
esophageal squamous cell carcinoma (1 paper, 2014). Esophageal squamous cell carcinoma (ESCC) is a type of esophageal carcinoma (EC) that can affect any part of the esophagus, but is usually located in the upper or middle third. "An increased expression of NDUFB9 also imparts a higher risk of lymph node metastasis in esophageal squamous cell carcinoma." (PMID 25050621, 2014).
neoplasms of the brain (1 paper, 2022). "Hence, NDUFB9 mutation in malignant brain tumors more so than in benign tumors suggests that mitochondrial dysfunction drives malignancy in neoplasms of the brain." (PMID 35887658, 2022). "Thus, NDUFB9 might induce those brain neoplasms to become malignant or benign via regulation of mitochondrial metabolism." (PMID 35887658, 2022). "Other SNP profiles revealed different molecules, including DDP6, NDUFB9, EDARADD, EST1, MC4R, LRP1B, and FRMD3, which perform different roles in brain neoplasms or malignancies." (PMID 35887658, 2022).
schizophrenia (1 paper, 2021). A major psychotic disorder characterized by abnormalities in the perception or expression of reality. "In our study, NDUFB9, the most robust candidate of the energy network involved in respiratory electron transport, was reduced in schizophrenia." (PMID 34576238, 2021).
cancer (9 papers, 2014 to 2026). A tumor composed of atypical neoplastic, often pleomorphic cells that invade other tissues. "NDUFB9 encodes an enzyme in the inner membrane of the mitochondria in humans and modulates mitochondrial function to affect the prognosis in cancers." (PMID 35887658, 2022). "According to certain studies, the four model genes EIF2S2, SNRPC, PRELID1, and NDUFB9 have significant roles in the development of cancer." (PMID 36185238, 2022). "To further investigate if NDUFB9 functions in cancer cell metastasis, we employed two independent shRNAs targeting NDUFB9 in MDA-MB-231 cell lines, and an empty vector (shCon) served as a control." (PMID 26641458, 2015).
tumor (7 papers, 2015 to 2025). "Furthermore, mutation of NDUFB9 (NADH dehydrogenase (ubiquinone) 1 beta sub-complex, 9) might lead to complex I deficiency, and promote tumor metastasis." (PMID 34489398, 2021). "Taken together, these data suggest that NDUFB9 might repress tumor metastasis." (PMID 26641458, 2015). "Therefore, the dysfunction of NDUFB9 leads to the overproduction of mitochondria-derived reactive oxygen species (mtROS) and the disturbance of the NAD+/NADH balance in tumor cells." (PMID 39418100, 2024).
mitochondrial disease (1 paper, 2021). "Many mitochondrial disease-related altered proteins also formed part of the energy network (DLD, NDUFA4, NDUFB5, NDUFB6, NDUFB9, NDUFS1, NDUFA12 and UQCRB) and belong to respiratory electron transport with the exception of DLD, which belongs to the TCA cycle." (PMID 34576238, 2021).
NDUFB9 also shares sentences with these, for which no sentence is quoted: smallpox (3 papers); Parkinson’s (2); viral infections (2); benign tumors (1); colorectal (1); colorectal cancer (1); cowpox (1); demyelination (1); hepatitis C virus infection (1); infection (1); lymph node metastasis (1); metabolic disorders (1); Myelopathy (1); pancreatic cancer (1); toxoplasmosis (1); type 2 diabetic (1); uveal melanoma (1).